SOX2 (SRY-box transcription factor 2)
Diseases named in the same sentence as SOX2 in open-access papers (continued):
Sharing a sentence is not in itself a finding about the gene and the disease.
fibrosarcoma (1 paper, 2019). A malignant mesenchymal fibroblastic neoplasm affecting the soft tissue and bone. "Collectively, these results indicate enhanced cellular plasticity in SIX1-expressing fibrosarcomas, as shown by the activation of Sox2 and additional markers of stemness or alternative cell linages, and the concomitant loss of mesenchymal markers." (PMID 30723235, 2019).
gallbladder carcinoma (1 paper, 2020). "Besides, Bufalin inhibited the tumor sphere formation capability of gallbladder carcinoma in matrigel, reduced the expression of multiple stemness-associated proteins, including Oct4, Sox2 and the stem cell-surface marker proteins CD133 and CD44." (PMID 32231716, 2020). "Western blot results suggested that Bufalin decreased the expression of stemness-associated surface proteins CD133 and CD44, and stemness-associated factors Sox2 and Oct4, which further illustrated that Bufalin has the inhibitory effect on gallbladder cancer stem cells." (PMID 32231716, 2020).
gastroesophageal reflux (1 paper, 2016). "BE is associated with gastroesophageal reflux which might change the expression profile of key transcription factors involved in the establishment of tissue differentiation, namely, SOX2 (associated with esophageal and gastric differentiation) and CDX2 (associated with intestinal differentiation)." (PMID 27766003, 2016).
germ cell cancers (1 paper, 2014). "Besides in these epithelial cancers, SOX2 has also been proven to be of diagnostic value in the context of human germ cell cancers (GCC)." (PMID 24404135, 2014).
Gorlin syndrome (1 paper, 2020). "When the reprogramming factors OCT4/3, SOX2, KLF4 and c-MYC were introduced into 4.0 x 105 cells, iPSCs generated from four patients with Gorlin syndrome were successfully generated and designated as G11-, G12-, G36- and G72-iPSC." (PMID 32436863, 2020).
hemangioblastoma (1 paper, 2015). "Thus, we explored the expression of SOX-2 in hemangioblastoma before and after propranolol treatment, and SOX-2 levels were also significantly decreased by propranolol." (PMID 26394686, 2015). "Notably, VEGF and EPO are HIF-1α targets involved in angiogenesis and oxygen supply to cells, while SOX2 is a transcriptional target of HIF-2α and is a stemness target implicated in the undifferentiated nature of the mesenchymal component predominant in hemangioblastomas." (PMID 26394686, 2015). "In fact, propranolol inhibited HIF-dependent transcription in a 9xHRE HeLa reporter cell line and the crucial gene targets for hemangioblastoma survival, such as VEGF, EPO and SOX2." (PMID 26394686, 2015).
hemangioma (1 paper, 2015). A benign vascular lesion characterized by the formation of capillary-sized or cavernous vascular channels. "mRNA and protein expression of neural crest and stem cell markers was previously confirmed in a panel of hemangioma samples, revealing variable expression levels for Oct4, Myc, Sox2, and Nanog." (PMID 26412983, 2015).
hemophilia A (1 paper, 2019). The most common form of hemophilia characterized by spontaneous or prolonged hemorrhages due to factor VIII deficiency. "Our quantitative real-time PCR (qPCR) results showed that gene-corrected cell lines expressed the pluripotent marker genes OCT4, SOX2, and LIN28 at levels similar to those of the parental hemophilia A patient-derived iPSC line." (PMID 30996250, 2019).
hepatoblastoma (1 paper, 2023). Hepatoblastoma (HB) is a malignant hepatic tumor and is the most common pediatric liver cancer. "We noted that the metastatic hepatoblastoma cell line, HLM_2, had higher levels of mRNA abundance of stemness markers Oct4, Nanog, Nestin, and Sox2 compared to the parent cell line, HuH6, so we sought to explore the effects of PIM kinase inhibition on metastatic hepatoblastoma stemness." (PMID 38203596, 2023).
HPRT deficiency (1 paper, 2013). "Therefore, the persistent and even increasing expression of Sox2 in the differentiating HPRT-deficient ESD3 cells in these studies is consistent with the impaired neurogenesis characteristic of HPRT deficiency." (PMID 24130677, 2013).
Hyperkeratosis (1 paper, 2013). Hyperkeratosis is a histopathological term defining a thickened stratum corneum and may be present in many different skin conditions, with many possible overlaps. "Histological observation of the skin of the CAP1/Prss8lox/Δ;Sox2::CreTg/+ pups right after birth showed hyperkeratosis." (PMID 23405214, 2013).
hyperlipidemia (1 paper, 2022). "Building upon these benchmark data, we sought to explore the impact of prolonged hyperlipidemia as well as the effect colchicine-based therapy on a variety of atheroprotective (Klotho, HOXA5, NOTCH1, and OCT4) and proatherogenic (HIF1a, SOX2, BMP4, and NANOG) genes." (PMID 36362692, 2022).
Hypertension (1 paper, 2015). The presence of chronic increased pressure in the systemic arterial system. "The analyses of SHR-specific genes using IPA revealed that B-cell CLL/lymphoma 6 (Bcl6) and SRY (sex determining region Y)-box 2 (Sox2) were possible candidate genes responsible for causing hypertension in SHRs." (PMID 26165378, 2015). "The IPA path explorer tool revealed that B-cell CLL/lymphoma 6 (Bcl6) and SRY (sex determining region Y)-box 2 (Sox2) were possible candidate genes that trigger hypertension in SHRs." (PMID 26165378, 2015).
IgA nephropathy (1 paper, 2022). "miRNA-127 controls embryonic stem cell pluripotency via the HMGB2-OCT/SOX2 axis, and miR-590-3p contributes to the severity of IgA nephropathy via downregulation of HMGB2 in peripheral mononuclear cells." (PMID 35159393, 2022).
infectious colitis (1 paper, 2017). A viral or bacterial infectious process affecting the large intestine. "We therefore examined the presence of Sox2 + Hu+ enteric neurons in patients with inflammatory or infectious colitis as a proxy for inflammation-induced neurogenesis and also to determine whether a similar Sox2+ cell may give rise to neurons in inflamed human colon." (PMID 28566702, 2017).
intracerebral haemorrhage (1 paper, 2015). "Moreover, MMP-2 expression is detected in SOX2 immunopositive progenitor cells in the teleost fish, while siRNA to select MMPs abrogates enhanced neurogenesis in a murine model of intracerebral haemorrhage." (PMID 26783471, 2015).
intrahepatic cholangiocarcinoma (1 paper, 2018). A carcinoma that arises from the intrahepatic bile duct epithelium in any site of the intrahepatic biliary tree. "All these results are consistent with the existing reports that high expression of SOX2 is associated with poor OS in intrahepatic cholangiocarcinomas." (PMID 30186173, 2018).
invasive ductal carcinoma (1 paper, 2022). "Additionally, the protein levels of SETD1A and SOX2 were significantly higher in invasive ductal carcinoma tissues than in the normal breast tissues." (PMID 35966598, 2022).
kidney injury (1 paper, 2024). Trauma to the kidney. "The mechanism of the miR-122-5p/SOX2 axis derived from USC-Exos in inhibiting inflammation and fibrosis after obstructive kidney injury discovered in this study may provide new molecular targets for the treatment of obstructive kidney injury." (PMID 38617751, 2024). "After overexpression of SOX2 in vitro, inflammation and fibrosis were remarkably enhanced, while the pathway proteins p-AKT and p-ERK1/2 were suppressed, indicating that SOX2 is positively correlated with inflammation and fibrosis and plays a negative regulatory role in obstructive kidney injury." (PMID 38617751, 2024).
lens agenesis (1 paper, 2018). "SOX2 and PAX6 mutations may cause lens induction failure, FOXE3 mutations are associated with lens agenesis, and OTX2, CHX10, and RAX may cause failure of retinal differentiation." (PMID 30153864, 2018).
liposarcoma (1 paper, 2020). A usually painless malignant tumor that arises from adipose tissue. "After EC8042 treatment, SORE6+ cells disappeared before apoptosis become evident, thus suggesting that EC-8042 was able to repress the expression of SOX2, as we previously observed in a related myxoid liposarcoma model." (PMID 32295077, 2020).
lung adenoma (1 paper, 2017). A benign, well circumscribed epithelial neoplasm that arises from the bronchus or the lung parenchyma. "Thus, expression of activated FoxM1-ΔN in lung adenomas increased tumor cell proliferation and induced SOX2." (PMID 29267283, 2017).
Lung Benign Tumor (1 paper, 2012). "All this indicates that Sox2 and Oct4 can be potential novel biomarkers to distinguish cancer from noncancerous lesions and benign lung tumors." (PMID 22837720, 2012).
lung tumors (1 paper, 2013). "In lung neoplasms SOX2 is frequently upregulated and its gene amplification correlates with protein overexpression in NSCLC." (PMID 23620753, 2013). "In the Yale cohort (validation set), SOX2 was measured in 335 lung tumors, including 76(22.69%) SCC, 212(63.28%) ADC and 47(14.03%) other histotypes." (PMID 23620753, 2013).
malaria (1 paper, 2008). Malaria is a serious and sometimes fatal disease caused by a parasite that commonly infects a certain type of mosquito which feeds on humans. "Nanog (fold = 4.5, q < 0.0005), Oct4 (fold = 2.3, q < 0.0005) and Sox2 (fold = 3.0, q < 0.0005) were all significantly downregulated in the PBMC from malaria infected patients compared to controls (GDS2362)." (PMID 19094235, 2008).
male infertility (1 paper, 2023). The inability of the male to effect fertilization of an ovum after a specified period of unprotected intercourse. "The observed variations in in vitro and in vivo expressions of Sox2 during spermatogenesis are important results that will help researchers better understand how the process and features might impact male infertility and other disorders caused by Sox2 mutations." (PMID 37663428, 2023). "Further research regarding the role of Sox2 expression in spermatogenesis might be useful in improving male infertility treatments." (PMID 37663428, 2023).
mantle cell lymphoma (1 paper, 2023). Mantle cell lymphoma is a rare form of malignant non-Hodgkin lymphoma affecting B lymphocytes in the lymph nodes in a region called the ``mantle zone''. "All nine patient samples had minimal/no expression of Sox2/Oct4 compared to SupM2 or Jeko-1 (a mantle cell lymphoma cell line)." (PMID 38203669, 2023).
megaureter (1 paper, 2022). "The m6A levels of BMP4, TBX18 and SOX2 mRNAs were lower in the ureter samples from patients with megaureter (M group) than those from patients with VUR (V group)." (PMID 35795641, 2022).
MELAS syndrome (1 paper, 2019). MELAS (Mitochondrial myopathy, encephalopathy, lactic acidosis, and stroke) syndrome is a rare progressive multisystemic disorder characterized by encephalomyopathy, lactic acidosis, and stroke-like episodes. "We reprogrammed fibroblasts from a seven year-old boy with MELAS syndrome harboring 95% mtDNA A3243G mutation to iPS cells using retroviral vectors expressing Oct4, Klf4, Sox2, and c-Myc." (PMID 30658448, 2019).
memory impairment (1 paper, 2024). "In experiments using behavioral tests and cell count methods similar to those used in this study, early-life exposure to neonicotinoid insecticides resulted in memory impairment and a decrease in SOX2-positive cells in the DG." (PMID 39050668, 2024).
Merkel cell carcinoma (1 paper, 2025). "Here, we show that MCPyV+ Merkel cell carcinoma is defined by neuroendocrine-lineage core regulatory (CR) transcription factors (TFs) (ATOH1, INSM1, ISL1, LHX3, POU4F3, and SOX2) that were essential for tumor survival and that co-bound chromatin with the viral small T antigen at super enhancers." (PMID 41392987, 2025).
multiple endocrine neoplasia type 1 (1 paper, 2020). An autosomal dominant tumor predisposition syndrome caused by pathogenic variants in the MEN1 gene, characterized by an increased risk of tumors of the parathyroid glands, pituitary gland, and foregut neuroendocrine tumors (most commonly pancreatic islet cells). "Additionally, in a neuroendocrine application, cells obtained from the urine of patients with multiple endocrine neoplasia type 1 syndrome (MEN1) were used to generate iPSCs with non-integrated episomal plasmids carrying Oct4, Sox2, Klf4, and miR-302-367 without using c-Myc." (PMID 31760627, 2020).
myoepithelioma (1 paper, 2013). "Only PSCA was observed in the myoepithelioma cell lines, with no expression of Sox-2, Nanog, or Oct3/4." (PMID 23761224, 2013).
nasal polyp (1 paper, 2021). "Over-expression of SOX2 has been reported in nasal polyp epithelial cells." (PMID 34439758, 2021). "Thus, DMRT3 along with SOX2 may regulate nasal polyp differentiation." (PMID 34439758, 2021).
neuroendocrine prostate tumors (1 paper, 2020). "Furthermore, the role of SOX2 has been reported in repressing adenocarcinoma specific genes by enhancing the expression and activity of lysine-specific demethylase 1A (LSD1/KDM1A), highlighting the potential of SOX2 as a lineage reprogramming factor in neuroendocrine prostate tumors." (PMID 32754615, 2020).
neurofibroma (1 paper, 2018). An intraneural or extraneural neoplasm arising from nerve tissues and neural sheaths. "Finally, we found that the expression of COL3A1 and SOX2 was increased in tranilast-resistant neurofibroma cells, suggesting that the encoded proteins may give rise to resistance to tranilast treatment." (PMID 29666462, 2018). "Combined treatment with a SOX2 blocker and tranilast is therefore also a potential approach to inhibition of neurofibroma growth." (PMID 29666462, 2018). "We established the tranilast-resistant neurofibroma cells derived from patient 1 that had been exposed to 250 μM tranilast for 20 days, and we found that the abundance of COL3A1 and SOX2 mRNAs was increased in the tranilast-resistant neurofibroma cells." (PMID 29666462, 2018). "Knockdown of type III collagen (COL3A1) also suppressed the proliferation of neurofibroma cells, whereas expression of COL3A1 and SOX2 was increased in tranilast-resistant cells, suggesting that COL3A1 and the transcription factor SOX2 might contribute to the development of tranilast resistance." (PMID 29666462, 2018).
ocular hypertension (1 paper, 2022). Abnormally high intraocular pressure. "Rat ONH of ocular hypertension for 5 weeks had more Sox2+ astrocytes than controls, and co-staining of Ki67 and Sox2 proved that 80% (anterior ONH) and 66% (transition zone of ONH) of mitotic cells were astrocytes." (PMID 36466782, 2022).
ocular tumors (1 paper, 2022). "To further characterize these tumors, we analyzed a subset of ocular tumors from ONI and control zebrafish for expression of blbp, sox2, and sox10." (PMID 35042909, 2022).
osteopetrosis (1 paper, 2019). Osteopetrosis, also known as marble bone disease, is a descriptive term that refers to a group of rare, heritable disorders of the skeleton characterized by increased bone density on radiographs. "All hiPSC lines derived from osteopetrosis patients expressed alkaline phosphatase and other stemness markers (SSEA4, OCT3/4, TRA1-60, SOX2) as revealed by immunofluorescence staining, flow cytometry (SSEA4, OCT3/4), and qRT-PCR." (PMID 31315669, 2019).
osteoporosis (1 paper, 2024). A condition of reduced bone mass, with decreased cortical thickness and a decrease in the number and size of the trabeculae of cancellous bone (but normal chemical composition), resulting in increased fracture incidence.
pancreatic adenocarcinoma (1 paper, 2020).
Papillary Craniopharyngioma (1 paper, 2024). A craniopharyngioma composed of sheets of squamous epithelium which separate to form pseudopapillae. "Furthermore, in papillary craniopharyngioma, BRAF V600E mutation could confer proliferative advantage to SOX2+ tumour cells." (PMID 39456573, 2024).
papillary thyroid cancer (1 paper, 2013). "After isolation, CD133+ cells exhibited higher radioresistance and higher expression of Oct4, Nanog, Sox2, Lin28 and Glut1 in the cell line or primarily cultured papillary thyroid cancer cells, and lower expression of various thyroid-specific genes, namely NIS, Tg, TPO, TSHR, TTF1 and Pax8." (PMID 23081821, 2013).
parathyroid adenomas (1 paper, 2021). "Nuclear SOX2 expression was detectable in 18% of parathyroid adenomas (PAds, n = 34) involving 5–30% of cells, while OCT4 and NANOG were expressed at the nuclear level in a more consistent subset of PAds involving 15–40% of cells." (PMID 34199594, 2021). "We tested the hypothesis that HAR1B mediates or contributes with menin to modulate the SOX2 expression in parathyroid adenomas." (PMID 34199594, 2021). "Considering that both CASR and YAP1 feature as tumor suppressors in parathyroid adenomas, the induction of SOX2 expression may promote cell resting more than cell proliferation." (PMID 34199594, 2021).
penile cancer (1 paper, 2020). A primary or metastatic malignant neoplasm that affects the penis. "Using a penile cancer cell line, SA1, established from an SA penile tumor, we generated shRNA-mediated Sox2 knockdown, which attenuated subcutaneous tumor growth of SA1." (PMID 32358507, 2020).
pharyngeal tumors (1 paper, 2020). "Strikingly, the impact of NANOG and SOX2 on outcome varied depending on tumor site and lymph node infiltration, specifically showing prognostic significance in pharyngeal tumors." (PMID 32635524, 2020).
plasma cell disorders (1 paper, 2011). "A single study has previously addressed SOX2-specific antibodies in plasma cell disorders." (PMID 22190969, 2011).
Pleural effusion (1 paper, 2019). The presence of an excessive amount of fluid in the pleural cavity. "In the paired tumor tissues, five metastatic lymph nodes or pleural effusions showed enhanced SOX2 expression compared with the corresponding primary tumors, while four of the five tissue pairs showed elevated TARBP2 expression." (PMID 30759864, 2019).